KRTAP10-3 (keratin associated protein 10-3)
Description:
In the hair cortex, hair keratin intermediate filaments are embedded in an interfilamentous matrix, consisting of hair keratin-associated proteins (KRTAP), which are essential for the formation of a rigid and resistant hair shaft through their extensive disulfide bond cross-linking with abundant cysteine residues of hair keratins. The matrix proteins include the high-sulfur and high-glycine-tyrosine keratins.
Synonyms: KAP10.3; KAP18-3; KRTAP10.3; KRTAP18-3; KRTAP18.3; KAP18.3
Tractability: No criterion of Open Targets' tractability assessment is met for any kind of drug.
Gene: Protein-coding gene on chromosome 21 (44,557,790 to 44,558,795, reverse strand). Ensembl gene ENSG00000212935.
Pathways (Reactome):
Developmental Biology: Keratinization
Gene Ontology:
Cellular component: cytosol; keratin filament
Genetic constraint (gnomAD): Missense variants: 249 observed, 223.24 expected, observed/expected ratio (o/e) 1.12, 90% interval 1 to 1.24. Synonymous variants: 100 observed, 94.3 expected, observed/expected ratio (o/e) 1.06, 90% interval 0.9 to 1.25.
Homologues: Paralogues in human: KRTAP10-9 (88% identical), KRTAP10-1 (87% identical), KRTAP10-11 (87% identical), KRTAP10-7 (83% identical), KRTAP10-5 (79% identical), KRTAP10-6 (78% identical), KRTAP10-4 (77% identical), KRTAP10-10 (77% identical), KRTAP10-12 (75% identical), KRTAP10-2 (74% identical), KRTAP10-8 (71% identical), KRTAP16-1 (41% identical), and 35 more.